WNT5A (Wnt family member 5A)
Diseases named in the same sentence as WNT5A in open-access papers (continued):
Sharing a sentence is not in itself a finding about the gene and the disease.
Sepsis (32 papers, 2011 to 2026). Sepsis is defined as life-threatening organ dysfunction caused by a dysregulated host response to infection. "In this prospective study, we investigated the association between Wnt5a expression and the persistence of kidney disease in patients with urosepsis, as the kidneys are frequently involved in sepsis." (PMID 38913943, 2024). "Wnt5A heterozygous mice are susceptible to polymicrobial sepsis, but it is not clearly known if this is due to defects in CD8 T cell-mediated immunity." (PMID 36091060, 2022). "In pathological states such as sepsis, cardiac arrhythmia associated with hypertension and chronic obstructive lung diseases, Wnt5A signaling is activated in the cardiovascular system." (PMID 34079452, 2021). "Patients with severe sepsis had elevated WNT5A serum levels, and patients with sepsis-associated acute respiratory distress syndrome displayed elevated WNT5A protein expression in lung tissue." (PMID 31781093, 2019). "Our research specifically focuses on Wnt5a, which has been implicated in rheumatoid arthritis, sepsis, and tuberculosis." (PMID 24346141, 2014). "CYP1B1 was high expression in Wnt5A-associated inflammatory, cardiovascular diseases, and sepsis." (PMID 39262873, 2024). "Upregulation of miR-23a-3p may alleviate LPS-induced cell injury by targeting wnt5a and inactivating Wnt/β-catenin pathway, which may serve as a novel therapeutic target for sepsis-associated AKI." (PMID 35239776, 2022). "The role of Wnt5a in sepsis has also been investigated, and it is reportedly elevated in patients with sepsis." (PMID 38913943, 2024). "Further research is required to understand the distinct pathophysiological mechanisms of the non-canonical pathway during the inflammatory process and to verify the role of Wnt5a as a novel bio-marker in populations with inflammatory disorders, such as sepsis." (PMID 38913943, 2024). "Further studies with larger numbers of subjects are needed to understand the spatio-temporal role of Wnt5a throughout the disease and to verify Wnt5a measurements as bio-markers in various inflammatory disease conditions, including sepsis." (PMID 38913943, 2024). "The dysregulation of the Wnt5a / SFRP5 system has already been demonstrated in a smaller study of 60 critically ill patients with sepsis." (PMID 36830849, 2023). "Firstly, the Wnt5a/SFRP5 system is not only dysregulated in sepsis alone, but also in critical illness in general." (PMID 36830849, 2023). "The mRNA expression of wnt5a was significantly upregulated and negatively correlated with miR-23a-3p expression in serum of sepsis-induced AKI patients." (PMID 35239776, 2022). "The expression levels of miR-23a-3p and wnt5a in sepsis-induced AKI patients and lipopolysaccharide (LPS)-treated HK-2 cells were detected by real-time PCR and western blotting." (PMID 35239776, 2022). "Studies have shown that WNT-5a is closely related to inflammatory bone resorption diseases such as rheumatoid arthritis, as well as inflammatory diseases such as sepsis and atherosclerosis." (PMID 34440994, 2021). "The lipid modified protein Wnt5A is emerging as a critical mediator of proinflammatory responses and disease severity in sepsis, hypertension and COVID-19." (PMID 34079452, 2021). "For example, a study reported significantly upregulated WNT5A levels in the serum of a sepsis patient and in the lung biopsy from a patient who died of sepsis, compared with the healthy-control levels." (PMID 34200709, 2021). "We intended to evaluate the significance of Wnt5A signaling in the context of pathogenic bacterial infections, which are known to be associated with exacerbation of COPD and sepsis." (PMID 29686674, 2018). "Previous studies report elevated levels of Wnt5A in sera of patients with severe sepsis and septic shock, that is corroborated by the finding of strongly induced synthesis and secretion of Wnt5A by TLR-activated macrophages." (PMID 28717346, 2017).
Sepsis (continued). "Other studies have shown that Wnt5a is upregulated in certain inflammatory diseases (e.g. rheumatoid arthritis, tuberculosis, and sepsis), and particularly by activated macrophages." (PMID 24346141, 2014). "Based on the observation by Pereira and colleagues, Wnt5a expression is increased in the sera of patients suffering from severe sepsis." (PMID 23935909, 2013). "The Wnt5A signaling pathway is activated in sepsis patients." (PMID 41509654, 2026). "Therefore, we suggest that Wnt5a levels can be a prognostic bio-marker in patients with sepsis and that serial measurements of this protein can help identify high-risk patients with persistent AKI and adverse clinical outcomes." (PMID 38913943, 2024). "Also, Wnt5a possesses pro-inflammatory properties in the pathogenesis of inflammatory diseases, including sepsis." (PMID 35239776, 2022). "The degree of CLP-induced sepsis in the context of Wnt5A signaling was also noted as a comparison." (PMID 29686674, 2018). "High levels of Wnt5A are found in sera of patients with sepsis and septic shock." (PMID 28717346, 2017). "This along with the present finding of highly induced Wnt5A expression in IL-4-activated VEC prompt further studies to investigate if Wnt5A contributes to vascular leakage and edema formation in severe systemic inflammatory diseases like sepsis/septic shock, and in IL-4 driven allergic inflammation." (PMID 28717346, 2017). "Another study indicates that Wnt5a could be an important factor that contributes to the dysfunction of DCs that develops during polymicrobial sepsis." (PMID 29075648, 2017). "Wnt5a may upregulate water reabsorption to compensate for plasma volume depletion in sepsis and may contribute to water retention in obese and metabolic syndrome patients." (PMID 27892464, 2016). "We chose to examine the modulation of WNT5A because it has been implicated in several pulmonary disorders and has not been studied in the context of sepsis and LPS-induced ARDS." (PMID 25331176, 2014). "Wnt5a signaling is known to be essential for the general inflammatory response and it is secreted in chronic inflamed site such as inflammatory synoviocytes, the atherosclerotic lesions, and the serum and bone marrow of patients with severe sepsis." (PMID 22485170, 2012). "Wnt5a expression is induced by mycobacterial cell wall components and endotoxin in human antigen-presenting cells, and Wnt5a signaling is essential for the general inflammatory response of human macrophages during sepsis." (PMID 22485170, 2012). "Observations of elevated WNT5A protein levels in serum of patients with severe sepsis highlights the possibility that WNT proteins produced in response to infection may act not only locally but also systemically, and thereby shape immune cell differentiation and functions at distant sites." (PMID 31781093, 2019). "Having previously demonstrated a role of Wnt5A signaling in phagocytosis, we proceeded to decipher the connection of Wnt5A signaling with infection by pathogenic bacteria, namely Pseudomonas aeruginosa (PA) and Streptococcus pneumoniae (SP), which are related with the progression of COPD and sepsis." (PMID 29686674, 2018). "However, in sepsis wnt5a was shown to be detectable in serum samples of affected subjects, suggesting that under special circumstances wnt5a might be released by inflamed tissues into the circulation." (PMID 22384249, 2012). "We concluded that miR-23a-3p suppressed the development of sepsis-induced AKI by downregulating Wnt/β-catenin pathway, at least in part, via targeting wnt5a." (PMID 35239776, 2022). "In fact, in a small study with 60 critically ill patients, the authors showed a dysregulation of the Wnt5a/SFRP5 system in human sepsis but did not observe statistical alterations in SFRP5 concentrations." (PMID 36830849, 2023).
Sepsis (continued). "We extended our in vitro findings by confirming that collagen synthesis and the main target gene products of this pathway (WNT5A, MMP7) increased in a clinically relevant model of sepsis-induced lung injury and in lungs from patients who died with severe sepsis and ARDS." (PMID 25331176, 2014). "In addition, Pereira’s study only emphasized the upregulation of Wnt5a expression in macrophages derived from sepsis patients, and did not further explore the effect of Wnt5a on macrophage differentiation." (PMID 32228612, 2020). "Targeting paracrine, as well as autocrine Wnt5A signalling by WIF1 may open novel therapeutic perspectives for the treatment of capillary leakage in systemic inflammatory conditions such as severe inflammation and sepsis, as well as allergic and autoimmune diseases." (PMID 28717346, 2017). "Interestingly, WNT-5A does not influence bacterial killing inside the phagosome prolonging presence of the antigen and as such might contribute to the development of sepsis by supporting sustenance of the microbial infection and persistence of proinflammatory macrophages at the site of infection." (PMID 26514730, 2016).
atherosclerosis (30 papers, 2011 to 2025). A disease characterized by the build-up of fatty material and calcium deposition in the arterial wall resulting in partial or complete occlusion of the arterial lumen. "Wnt5a has also been associated with inflammatory diseases like rheumatoid arthritis and atherosclerosis." (PMID 35622188, 2023). "V55 reduced expression of Icam-1, Wnt5a and Mmp7 (associated to inflammation and tissue destruction in periodontitis) and Scd1, Scd2, Egf1 (correlated to atherosclerosis)." (PMID 35631379, 2022). "Obesity predisposes to decreased SFRP5 and increased WNT5A expression, which has been confirmed in human cohorts with atherosclerosis." (PMID 34948320, 2021). "WNT5A has been implicated in cellular inflammation, proliferation, and migration to notably develop atherosclerosis and insulin resistance." (PMID 34948320, 2021). "Furthermore, Wnt5a was involved in vascular calcification, a hallmark of advanced atherosclerosis." (PMID 27608847, 2016). "Based on the obtained data, our study aimed to evaluate the therapeutic potential of tetrandrine, in low and high doses, in vitamin D3/HCD-induced atherosclerosis rat model via regulating miRNA-34a and the Wnt5a/Ror2/NF-κB pathway." (PMID 39266573, 2024). "This study aimed to evaluate the therapeutic potential of tetrandrine in high cholesterol diet (HCD)-induced atherosclerosis, in rats, via modulation of miR-34a, as well as, Wnt5a/Ror2/ABCA1/NF-κB pathway and to compare its efficacy with atorvastatin." (PMID 39266573, 2024). "This highlights the ability of tetrandrine to ameliorate atherosclerosis in rats via modulating miR-34a as well as Wnt5a/Ror-2/ABCA1/ NF-κB pathway." (PMID 39266573, 2024). "The literature highlighted the role of Wnt5a/Ror-2/ABCA1/NF-κB in the pathogenesis of atherosclerosis." (PMID 39266573, 2024). "Perturbations in Wnt5a signaling have been reported in various inflammatory diseases such as rheumatoid arthritis, atherosclerosis and psoriasis." (PMID 39266573, 2024). "Recent research shows that miR-141-3p reduces cell migration and proliferation by targeting Wnt5a in atherosclerosis model." (PMID 36680208, 2023). "ROR2 was included as a co-receptor of FZD5 because it was proposed as a proinflammatory receptor for Wnt5a in atherosclerosis and lung COPD." (PMID 35622188, 2023). "For instances, Wnt5A protein and mRNA has been described as being expressed in different inflammatory conditions such as RA, atherosclerosis (ATH), and tuberculosis." (PMID 34860323, 2022). "V55 diminished the expression of Icam-1, Egfr, Wnt5a and Mmp7 (related to inflammation and tissue damage in periodontal disease) and Scd1, Scd2, Egf1 (related to atherosclerosis)." (PMID 35631379, 2022). "In our previous study, we have found that the expression of Wnt5a is notably up-regulated in both patients with atherosclerosis and apoE-/- mice." (PMID 34326694, 2021). "Wnt5a also acts as an inflammatory mediator and contributes to impaired endothelial function in diabetes, atherosclerosis, and rheumatoid arthritis." (PMID 33462195, 2021). "In essence, the aberrant WNT5a/SOX9 signal transmission in atherosclerosis seems to set the stage to initiate atherosclerotic calcification." (PMID 33322009, 2020). "In spite of WNT5A has been particularly investigated in the progression of atherosclerosis, studies on the relationship between WNT5A and SFRP5 in cardiovascular diseases are limited." (PMID 33192583, 2020). "The expression of Wnt5a in endothelial cells and smooth muscle cells, is involved in the development of atherosclerosis." (PMID 32982804, 2020). "Therefore, the current study's goal was to evaluate tetrandrine's therapeutic potential in a rat atherosclerosis model by modifying the miR-34a and Wnt5a/Ror2/NF-κB cue." (PMID 39266573, 2024). "We concluded from all of the previous findings that miR-34a together with Wnt5a/Ror2/NF-κB trajectory could have a great role in the pathophysiology of atherosclerosis." (PMID 39266573, 2024).
atherosclerosis (continued). "Furthermore, the serum concentration of Wnt5a is significantly increased in severely obese patients (BMI > 40 kg/m2) and is positively correlated with atherosclerosis and cardiovascular risk." (PMID 33462195, 2021). "Moreover, increased WNT5a levels in obese patients were found, and some author suggested a link between sFRP5 and WNT5a in atherosclerosis." (PMID 33322009, 2020). "Moreover, ox-LDL triggers atherosclerosis by increasing the expression of Wnt5a in human macrophages and differentiated THP-1 cells." (PMID 32982804, 2020). "However, we found that as atherosclerosis advances, although Wnt5a protein was increased, WISP‐1 was reduced." (PMID 30548452, 2019). "Furthermore, oxLDL which is a very well-known protagonist in atherosclerosis progression, also upregulates the mRNA expression of WNT-5a in THP-1 cells and monocyte-derived macrophages." (PMID 32195204, 2019). "Furthermore, macrophage-derived Wnt5a is involved in insulin resistance, atherosclerosis and cancer." (PMID 27608847, 2016). "Moreover, a positive feedback loop between IL6 and WNT5a exists in other diseases, which may indicate a similar mechanism in atherosclerosis." (PMID 33322009, 2020). "Interestingly, ARL4C promoted the expression of LRP6, WNT5A, and WNT11, which suggests that ARL4C suppresses atherosclerosis development by enhancing LRP6 expression." (PMID 40176913, 2025). "Similarly, the WNT5a concentration of serum was found to correlate with VC and CHD in obese patients with atherosclerosis." (PMID 33322009, 2020). "In the non-canonical pathway, WNT-5a is postulated to release Ca2+ by activating phospholipase C. The elevation of Ca2+ in the cells activates either calmodulin-dependent protein kinase II (CAMKII) or protein kinase C (PKC) which might play a pathogenic role in atherosclerosis." (PMID 32195204, 2019). "As aging is a risk factor for atherosclerosis, it was hypothesized that failure of Wnt5a to promote VSMC survival and WISP‐1 expression in advanced atherosclerosis may be due to aging." (PMID 30548452, 2019). "Oxidized Low density lipoprotein (Ox-LDL), but not native-LDL, induced Wnt5a expression in human macrophages, supporting the notion that macrophage-derived Wnt5a plays a positive role in atherosclerosis." (PMID 27608847, 2016). "Finally, PKN3 has been recently demonstrated to play a role in bone resorption downstream of non-canonical Wnt5a/ Ror2 signaling cascade that regulates the secretion of pro-inflammatory cytokines necessary for atherosclerosis development." (PMID 33092266, 2020).
osteosarcoma (28 papers, 2009 to 2025). A usually aggressive malignant bone-forming mesenchymal neoplasm, predominantly affecting adolescents and young adults. "Bioinformatics analysis identified six exosome‐associated osteosarcoma genes (WNT5A, GCA, ANXA6, BIRC5, IL1β, and ARPC3) that could serve as potential biomarkers." (PMID 40616392, 2025). "In addition, we find that Wnt5a/6 are up-regulated in-Ptch1 deficient MSCs and that β-Catenin is highly activated in mouse enchondroma and osteosarcoma samples." (PMID 31482846, 2019). "The observed anti-apoptotic effect of FHL2 silencing in osteosarcoma cells may be linked in part to the observed decrease in Wnt5a, since this protein exerts anti-apoptotic activity in cells of the osteoblast lineage." (PMID 23383046, 2013). "Previous studies proved that miR-217 acts as a potential tumor suppressor via regulating Wnt5a expression in osteosarcoma." (PMID 33958507, 2021). "Here, we demonstrates that ROR2 receptor activates PI3K/Akt/RhoA signaling and mediates Wnt5a-induced the migration of osteosarcoma cells." (PMID 29213214, 2017). "Taken together, we demonstrate that RhoA acts as the downstream of PI3K/Akt signaling (specific PI3Kα, Akt1 and Akt2 isoforms) and mediated Wnt5a-induced the migration of osteosarcoma cells." (PMID 28289332, 2017). "Our previous study finds that Wnt5a mediates the migration of osteosarcoma cells via elevating the PI3K/Akt and RhoA signaling." (PMID 29213214, 2017). "Wnt5a-induced osteosarcoma cell migration was largely abolished by shRNA or siRNA specific against ROR2." (PMID 29213214, 2017). "We have reported that the phosphatidylinositol-3 kinase (PI3K)/Akt signaling pathway mediated Wnt5a-induced osteosarcoma cell migration." (PMID 28289332, 2017). "To assess the effect of ROR2 receptors on Wnt5a-induced osteosarcoma cell migration, we generated the stable ROR2 knockdown MG-63 cells and transfected U2OS cells with specific siRNA targeting ROR2 and measured the cell migration by wound healing assays." (PMID 29213214, 2017). "Here, we demonstrates that RhoA acts as the downstream of PI3K/Akt signaling and mediated Wnt5a-induced the migration of osteosarcoma cells." (PMID 28289332, 2017). "In this study, overexpression of constitute active RhoA rescues Wnt5a-induced cell migration blocked by shRNA or siRNA against ROR2 in osteosarcoma cells." (PMID 29213214, 2017). "Osteosarcoma cells, pretreated with 10 nmol/L MK-2206 (Akt inhibitor) for 1 h, were incubated with 100 ng/mL of Wnt5a." (PMID 28289332, 2017). "We present the evidence here that RhoA mediates Wnt5a-induced osteosarcoma cell migration via PI3Kα, Akt1 and Akt2 isoforms." (PMID 28289332, 2017). "We present the evidence here that ROR2 mediates Wnt5a-induced osteosarcoma cell migration via PI3K/Akt and RhoA signaling." (PMID 29213214, 2017). "To assess the effect of Wnt5a on Rho activation in human osteosarcoma cells, we treated MG-63 and U2OS cells with 100 or 200 ng/mL Wnt5a, and measured the Rho activation by small G-protein activation assay." (PMID 28289332, 2017). "Treating human osteoblast-like osteosarcoma SaOS-2 cells with rhWnt5a for 10 days reduced the mineralization capacity of these cells, suggesting that Wnt5a has a direct effect on the mineralization potential of osteoblasts." (PMID 28777797, 2017). "In conclusion, RhoA acts as the downstream of PI3K/Akt signaling (specific PI3KαAkt1 and Akt2 isoforms) and mediated Wnt5a-induced the migration of osteosarcoma cells." (PMID 28289332, 2017). "Given that PI3Kα/Akt signaling (specific PI3Kα, Akt1 and Akt2 isoforms) mediate Wnt5a-induced the migration of osteosarcoma cells, we propose that PI3Kα/Akt act as the downstream of Wnt5a and ROR2." (PMID 29213214, 2017). "In the previous study, we found that the PI3K/Akt signaling pathway mediated Wnt5a-induced osteosarcoma cell migration." (PMID 28289332, 2017).